ST14 (ST14 transmembrane serine protease matriptase)
Description:
Exhibits trypsin-like activity as defined by cleavage of synthetic substrates with Arg or Lys as the P1 site. Involved in the terminal differentiation of keratinocytes through prostasin (PRSS8) activation and filaggrin (FLG) processing. Proteolytically cleaves and therefore activates TMPRSS13.
Synonyms: MT-SP1; PRSS14; SNC19; TADG15; HAI; TMPRSS14; CAP3; ARCI11; MTSP1
Tractability: Small molecule: a structure with a bound ligand is known; a high-quality ligand is known; it belongs to a druggable protein family. Antibody: its Gene Ontology location is reachable by antibodies, with high confidence; UniProt predicts a signal peptide or a membrane-spanning region. PROTAC: ubiquitination databases record sites on it; its protein half-life has been measured; a small molecule that binds it is known.
Target class: Serine protease; Enzyme; Serine protease PA clan; Serine protease S1A subfamily; Protease
Chemical probes: PD080763
Gene: Protein-coding gene on chromosome 11 (130,159,746 to 130,210,367, forward strand). Ensembl gene ENSG00000149418.
Subcellular location: Membrane
Subcellular location (Human Protein Atlas): Nucleoplasm; Vesicles
Pathways (Reactome):
Developmental Biology: Formation of the cornified envelope
Gene Ontology:
Molecular function: serine-type peptidase activity; serine-type endopeptidase activity
Biological process: keratinocyte differentiation; proteolysis; protein processing; animal organ development; epithelial cell differentiation
Cellular component: plasma membrane; external side of plasma membrane; extracellular region; membrane
Genetic constraint (gnomAD): Loss-of-function variants: 44 observed, 96.1 expected, observed/expected ratio (o/e) 0.46, 90% interval 0.36 to 0.59. The upper end of that interval is the gene's LOEUF score, 0.59, which puts it in group 2 of 6, group 1 being the genes least tolerant of losing a copy. Missense variants: 1,066 observed, 1,187.4 expected, observed/expected ratio (o/e) 0.9, 90% interval 0.85 to 0.94. Synonymous variants: 506 observed, 491.96 expected, observed/expected ratio (o/e) 1.03, 90% interval 0.95 to 1.11.
Homologues: Orthologues: chimpanzee ST14 (99% identical), macaque ST14 (94% identical), mouse St14 (82% identical), rat St14 (80% identical), pig ST14 (79% identical), rabbit ST14 (76% identical), guinea pig ST14 (76% identical), dog ST14 (73% identical), tropical clawed frog st14 (55% identical), zebrafish st14 (45% identical), Drosophila melanogaster Sb (19% identical), Drosophila melanogaster CG17242 (6% identical). Paralogues in human: TMPRSS7 (30% identical), TMPRSS6 (28% identical), TMPRSS15 (25% identical), TMPRSS9 (19% identical), TMPRSS13 (19% identical), TMPRSS2 (17% identical), TMPRSS3 (16% identical), TMPRSS11E (16% identical), TMPRSS5 (16% identical), HPN (15% identical), TMPRSS11F (14% identical), TMPRSS11D (14% identical), and 5 more.
Diseases named in the same sentence as ST14 in open-access papers:
ST14 is named in the same sentence as 74 diseases in open-access papers, as found by Europe PMC text mining. Sharing a sentence is not in itself a finding about the gene and the disease. The quoted sentences say what the papers report.
breast carcinoma (18 papers, 2012 to 2025). "Studies have found that ST14 single nucleotide polymorphisms can independently predict a poor survival rate for breast cancer; that is, ST14 gene mutations affect the prognosis of tumors." (PMID 38468232, 2024). "Our previous study showed that another member of the TTSP family, matriptase (encoded by the ST14 gene), is associated with breast cancer survival." (PMID 26014348, 2015). "We have previously found that in the Eastern Finnish population, a variant in the ST14 gene, rs704624, is associated with a poor patient outcome and low matriptase mRNA expression in breast cancer patients." (PMID 25029565, 2014). "High protein expression of ST14 has been shown in the epithelial-to-mesenchymal transition (EMT) of malignant cells isolated from human breast carcinomas." (PMID 38339272, 2024). "In tumors, ST14 promotes cell invasion, migration, and other malignant biological behaviors in breast cancer and prostate cancer." (PMID 38468232, 2024). "The expression of ST14 mRNA was significantly increased in bladder cancer, breast cancer, lung cancer, ovarian cancer, prostate cancer, and other cancer, and the expression was decreased in kidney cancer, melanoma, and sarcoma." (PMID 38468232, 2024). "In our earlier careful analysis of TCGA breast cancer patients, we showed that Prss14/epithin (ST14) is an excellent prognostic marker for highly metastatic ER− breast cancer." (PMID 32241917, 2020). "The importance of Prss14/ST14 in breast cancer progression, metastasis, and patient’s survival is now clear." (PMID 31426843, 2019). "Using several immunocompetent models, we verified that the importance of Prss14/ST14 roles in metastasis in breast cancer." (PMID 31426843, 2019). "In this study, we showed that Prss14/ST14 is a critical marker for breast cancer metastasis and a therapeutic target." (PMID 31426843, 2019). "In this report, we show that Prss14/ST14 is critically involved in lung metastasis of mouse breast cancer, and that an epitope containing the autocatalytic loop portion of the Prss14/ST14 protein can function as a preventive metastasis vaccine." (PMID 31426843, 2019). "The survival of mice orthotopically transplanted with 4 T1 or E0771 breast cancer cells were significantly increased when Prss14/ST14 was knocked-down." (PMID 31426843, 2019). "The ratios of ST14/Prss14 to its inhibitors showed minor correlative difference with survival rates of breast cancer patients." (PMID 27167193, 2016). "In this report, we evaluated ST14/Prss14 for a prognosis marker and a therapeutic target to ER− breast cancer by utilizing various public data." (PMID 27167193, 2016). "Knockdown of miR-27b augmented Nischarin (NISCH) and suppressor of tumorigenicity 14 (ST14) expression in human breast cancer, down-regulated STAT3, c-myc and cyclin D1 in glioma." (PMID 26910911, 2016). "We next positioned ST14/Prss14 in clusters with particular EMT signature genes in breast cancer patients to find clues for the specific role of ST14/Prss14 in the EMT process that we described earlier." (PMID 27167193, 2016). "To elucidate the role of a type II transmembrane serine protease, ST14/Prss14, during breast cancer progression, we utilized publically accessible databases including TCGA, GEO, NCI-60, and CCLE." (PMID 27167193, 2016). "Network analysis of expression profiles of ST14/Prss14 substrates and its interactors revealed a context dependent behavior in breast cancer." (PMID 27167193, 2016). "ST14/Prss14 is one of such genes: its expression was low in ERlow breast cancer cell lines, clustered together with CDH1 and its two inhibitors, SPINT1 and SPINT2." (PMID 27167193, 2016). "Through the analyses, we suggest that ST14/Prss14 is an excellent prognosis marker and therapeutic target for ER−/TN breast cancers." (PMID 27167193, 2016). "As seen in the coexpression analysis of known substrates, only part of known ST14/Prss14 functions are likely to be active in a breast cancer context." (PMID 27167193, 2016).
breast carcinoma (continued). "In this study, we attempted to clarify the role of ST14/Prss14 in breast cancer progression and patients' survival using public databases of gene expression profiles." (PMID 27167193, 2016). "Although the numbers of data in the TCGA breast cancer database are extremely low and all TN patients show high ST14/Prss14 expression, the pattern showed poor survival in ST14/Prss14high patients regardless of HER2 expression." (PMID 27167193, 2016). "Expressions of ER and ST14/Prss14 in TCGA and GEO breast cancer patients are clearly in separate populations." (PMID 27167193, 2016). "Three transcription factors, GRHL1, VGLL1, and ELF5 are strong candidates for the cell autonomous regulation of ST14/Prss14 in basal type ER− breast cancer patients and ER+ luminal A type breast cancer cell lines." (PMID 27167193, 2016). "In the case of MCF7, a luminal A type ER+ ST14/Prss14 expressing breast cancer cell line, ST14/Prss14 expression was diminished when ER expression was depleted by siRNA." (PMID 27167193, 2016). "The introduction of pre-miR-27b stimulates invasion in breast cancer cells by targeting the ST14 tumor suppressor, and is upregulated in glioma cells and tumor tissues." (PMID 23522567, 2013). "ST14 was first detected in the culture medium of breast cancer cells cultured in vitro in 1993." (PMID 38468232, 2024). "For example, the type II serine transmembrane protease Matriptase-1, also named Suppressor of tumorigenicity 14 (St14), has been reported as a potential oncogene in a wide range of epithelial derived cancers, including breast cancer, colorectal cancer, and squamous cell carcinomas." (PMID 37566613, 2023). "ST14 typically decreases breast cancer cell proliferation and invasion, so antitumor effects upon inactivation of miR-23b and miR-27b may depend on promotion of ST14 activity." (PMID 35508982, 2022). "Other studies showed that miR-27b could promote the proliferation and invasion of breast cancer cells by inhibiting the expression of ST-14." (PMID 33015156, 2020). "We showed Prss14/ST14 is a strong prognosis marker for highly mortal ER− breast cancer patients." (PMID 31426843, 2019). "Therefore, regulation of ST14/Prss14 is independently regulated by different mechanisms in ER+ and ER− breast cancer cell lines." (PMID 27167193, 2016). "ST14/Prss14 is located in the clusters of ER− breast cancer patients but in the ER+ cell lines." (PMID 27167193, 2016). "Previously, we reported that ST14/Prss14 can enhance metastasis in a mouse breast cancer model." (PMID 27167193, 2016). "To investigate whether the conclusion drawn from the mouse study is valid in human breast cancer patient population, we searched ST14/Prsss14 expression by using a well-documented TCGA BRCA database." (PMID 27167193, 2016). "Next, we wondered whether ST14/Prss14 expression shows any degree of correlation with the stages of TCGA breast cancer used in this analysis." (PMID 27167193, 2016). "Interestingly, a majority of YBX1 and HIF1A positive populations in ER−/low breast cancers are also ST14/Prss14 high expressors." (PMID 27167193, 2016). "We attempted to analyze ST14/Prss14 expression status with known molecular markers that could separate breast cancers into subgroups." (PMID 27167193, 2016). "Motivated by our previous findings, we hypothesized that in addition to ST14 and TMPRSS6, genes coding TTSPs and related genes exist as variants associated with breast cancer risk and patient outcome." (PMID 25029565, 2014). "The expression levels of Prss14/epithin (ST14), PKCβ (PRKCB), and three JNKs (MAPK8, MAPK9, and MAPK10) in more aggressive ER-negative (ER−) and less aggressive ER-positive (ER+) breast cancer patients were compared individually in the plot." (PMID 32241917, 2020). "Specific Prss14/ST14 staining in the cytoplasm, cell contacts, and the membrane were detected in human breast cancer cells, MCF7 and T47D." (PMID 31426843, 2019).
breast carcinoma (continued). "In order to assess the role of Prss14/ST14 on the breast cancer progression and metastasis, we used two mouse breast cancer cell lines, highly metastatic 4 T1 and less metastatic E0771, and their syngeneic mouse hosts, Balb/c and C57BL/6 strains, respectively." (PMID 31426843, 2019). "Because ST14/Prss14 can be activated by an autoactivation mechanism, it may work as a master key activating these substrates and thus initiating various signaling pathways on cancer cells (and/or stromal and immune cells nearby) during ER− breast cancer progression and metastasis." (PMID 27167193, 2016). "In order to further verify the regulatory mechanism of ST14/Prss14 expression, we decided to examine expression of EMT signature genes in cultured breast cancer cell lines." (PMID 27167193, 2016). "For breast cancer patients with little HER2 expression, ST14/Prss14 expression is especially useful as a prognosis marker, and therefore for a therapeutic target." (PMID 27167193, 2016). "Our initial search for the clues of ST14/Prss14′s roles in the EMT process was done by clustering a total of 1085 selected EMT signature genes from TCGA and GEO breast cancer patient data." (PMID 27167193, 2016). "Recent studies in MCF7 breast cancer cells demonstrated that KO of miR-23b and miR-27b gene expression using CRISPR systems alleviated tumor growth in xenograft nude mice by upregulation of ST14 (suppression of tumorigenicity 14)." (PMID 35508982, 2022). "Prss14/ST14 is critically involved in the metastasis of breast cancer and poor survival rather than primary tumor growth in two mouse models." (PMID 31426843, 2019). "In order to develop a new immunotherapeutic agent targeting metastatic breast cancers, we chose to utilize autocatalytic feature of the membrane serine protease Prss14/ST14, a specific prognosis marker for ER negative breast cancer as a target molecule." (PMID 31426843, 2019). "The survival of ER− breast cancer patients with high expression level of Prss14/ST14 is extremely poor while no death was apparent with patients with low expression level." (PMID 31426843, 2019). "Survival of breast cancer patients with higher levels of ST14/Prss14 expression is poor for all breast cancer populations regardless of cancer stages." (PMID 27167193, 2016). "Therefore, TFs which are expressed highly in ER−/low breast cancer populations have a strong connection to cancer progression and metastasis through EMT as well as to regulation of the expressions of ST14/Prss14." (PMID 27167193, 2016). "Survival of breast cancer patients with high ST14/Prss14 expression is significantly poor in estrogen receptor (ER) negative populations regardless of the ratios of ST14/Prss14 to its inhibitors, SPINT1 or SPINT2." (PMID 27167193, 2016). "Here, we report that ST14/Prss14 is an emerging therapeutic target for breast cancer where HER2 is not applicable." (PMID 27167193, 2016). "Therefore, an expression analysis of ST14/Prss14, for example by classical immunohistochemical analysis as performed in earlier reports, together with those of ER and HER2 would provide an added benefit to predict the prognosis of breast cancer patients." (PMID 27167193, 2016). "Moreover, ST14/Prss14 is a highly potential therapeutic target in TN breast cancers when Herceptin is not an option." (PMID 27167193, 2016). "In order to examine whether the poor survival is due to high ST14/Prss14 expression, and not due to the absence of HER2 in TN, we tried to compare the survival of ST14/Prss14high and ST14/Prss14low populations in the HER2 and TN breast cancer groups." (PMID 27167193, 2016).
prostate carcinoma (7 papers, 2005 to 2024). A carcinoma that arises from epithelial cells of the prostate gland. "ErbB-2 signal transduction upregulates the activity of ST14, which in turn promotes the invasion of prostate cancer cells." (PMID 38468232, 2024). "ST14 activation can increase the migration and invasion of prostate cancer cells and promote tumorigenicity and tumor metastasis." (PMID 38468232, 2024).
ichthyosis (5 papers, 2017 to 2022). Disorders of cornification that are characterized by visible scaling and/or hyperkeratosis of most or all of the skin. "Using a targeted next-generation sequencing array of 38 ichthyosis-associated genes on a large cohort of 180 ichthyosis patients from a primarily consanguineous background, a previously unreported homozygous p.Asp482Asn mutation in ST14 was identified in a patient with IHS." (PMID 29208051, 2017). "Per OMIM, ST14 is related to ichthyosis with hypotrichosis syndrome in a recessive inheritance manner." (PMID 34440371, 2021). "Mutations in the ST14 gene, encoding the serine protease matriptase, have been associated with ichthyosis-hypotrichosis syndrome (IHS), a Mendelian disorder with skin and hair manifestations which include, in addition to ichthyosis and hypotrichosis, hypohidrosis and follicular atrophoderma." (PMID 29208051, 2017). "In humans, ST14 variants may cause autosomal recessive congenital ichthyosis 11 (ARCI11, OMIM #602400), which can be further subclassified into autosomal recessive ichthyosis with hypotrichosis (ARIH) and ichthyosis, follicular atrophoderma, hypotrichosis, and hypohidrosis (IFAH)." (PMID 28235824, 2017).
colon carcinoma (4 papers, 2016 to 2021). "Our observation that induced CDX2 expression in LS174T cells promotes an increased ST14/SPINT1 ratio does not correlate with the reported expression pattern of decreased CDX2 levels and increased ST14/SPINT1 levels during colon cancer progression." (PMID 30087389, 2018). "However, as the name suggests, ‘suppression’ of tumors by ST14/Prss14 was claimed based on the observation that the expression is reduced in colon cancer." (PMID 27167193, 2016). "GO enrichment analysis showed that specific proteins, including TGFβ1, adenomatous polyposis coli (APC), CTNB1, low-density lipoprotein receptor-related protein (LRP) 5 (LRP5), LRP6, JAK1, ST14, and TP53BP1, were hypothetical CD151-interacting proteins in colon cancer." (PMID 33767593, 2021).